ATP5F1D (ATP synthase F1 subunit delta)
Description:
Subunit delta, of the mitochondrial membrane ATP synthase complex (F(1)F(0) ATP synthase or Complex V) that produces ATP from ADP in the presence of a proton gradient across the membrane which is generated by electron transport complexes of the respiratory chain (Probable). ATP synthase complex consist of a soluble F(1) head domain - the catalytic core - and a membrane F(1) domain - the membrane proton channel. These two domains are linked by a central stalk rotating inside the F(1) region and a stationary peripheral stalk. During catalysis, ATP synthesis in the catalytic domain of F(1) is coupled via a rotary mechanism of the central stalk subunits to proton translocation (Probable). In vivo, can only synthesize ATP although its ATP hydrolase activity can be activated artificially in vitro (By similarity). With the central stalk subunit gamma, is essential for the biogenesis of F(1) catalytic part of the ATP synthase complex namely in the formation of F1 assembly intermediate.
Synonyms: ATP5D; MC5DN5
Tractability: Small molecule: a structure with a bound ligand is known. PROTAC: ubiquitination databases record sites on it.
Gene: Protein-coding gene on chromosome 19 (1,241,746 to 1,244,825, forward strand). Ensembl gene ENSG00000099624.
Subcellular location: Mitochondrion; Mitochondrion inner membrane
Subcellular location (Human Protein Atlas): Mitochondria; Principal piece; Connecting piece; Flagellar centriole
Pathways (Reactome):
Metabolism: Formation of ATP by chemiosmotic coupling
Organelle biogenesis and maintenance: Cristae formation
Gene Ontology:
Molecular function: protein binding; proton-transporting ATP synthase activity, rotational mechanism; structural molecule activity; ADP binding; ATP binding
Biological process: aerobic respiration; mitochondrial proton-transporting ATP synthase complex assembly; proton motive force-driven mitochondrial ATP synthesis; proton motive force-driven ATP synthesis; response to copper ion
Cellular component: mitochondrion; proton-transporting ATP synthase complex; mitochondrial inner membrane; mitochondrial matrix
Genetic constraint (gnomAD): Loss-of-function variants: 16 observed, 9.1 expected, observed/expected ratio (o/e) 1.76, 90% interval 1.12 to 1.96. That is too few expected variants to judge how well the gene tolerates losing a copy. Missense variants: 294 observed, 193.08 expected, observed/expected ratio (o/e) 1.52, 90% interval 1.38 to 1.68. Synonymous variants: 129 observed, 86.57 expected, observed/expected ratio (o/e) 1.49, 90% interval 1.29 to 1.72.
Gene-disease validity (ClinGen):
ClinGen rates the evidence that ATP5F1D causes each of these diseases.
mitochondrial disease (autosomal recessive): Limited.
Homologues: Orthologues: chimpanzee ATP5F1D (100% identical), macaque ATP5F1D (98% identical), guinea pig ATP5F1D (90% identical), dog ATP5F1D (89% identical), rat Atp5f1d (88% identical), mouse Atp5f1d (86% identical), pig ATP5F1D (71% identical), zebrafish atp5f1d (68% identical), tropical clawed frog atp5f1d (67% identical), Caenorhabditis elegans F58F12.1 (45% identical), Drosophila melanogaster ATPsyndelta (44% identical).
Diseases named in the same sentence as ATP5F1D in open-access papers:
ATP5F1D is named in the same sentence as 20 diseases in open-access papers, as found by Europe PMC text mining. Sharing a sentence is not in itself a finding about the gene and the disease. The quoted sentences say what the papers report.
COVID-19 (2 papers, 2023). A disease caused by infection with severe acute respiratory syndrome coronavirus 2. "Interestingly, we also found that ATP synthesis-related genes (e.g., ATP5F1A, ATP5F1B, ATP5F1C, ATP5F1D, ATP5F1E) were significantly increased in COVID-19 patients." (PMID 37087411, 2023).
tumor (7 papers, 2018 to 2023). "In addition, we found that many genes associated with ATP synthesis, such as ATP5F1D, ATP5ME, and ATP5MF, and genes associated with NADH oxidation, such as NDUFS8, NDUFB10, and NDUFC1, were overexpressed in LIHC and LUAD tumor tissues." (PMID 33262783, 2020).
cancer (3 papers, 2021 to 2024). A tumor composed of atypical neoplastic, often pleomorphic cells that invade other tissues. "Through modifying the expression of m1A-methylated ATP synthase F1 subunit delta (ATP5D) mRNA, ALKBH3 stimulates the glycolysis of cancer cells." (PMID 39459530, 2024). "Whereas the precise functions of NDUFA3, NDUFA13 (also called GRIM19), COX7A1, COX4I2 and ATP5F1D in oxidative phosphorylation remain somewhat poorly understood, increased expression of NDUFA4L2 is known to drive pro-oncogenic phenotypes in numerous cancer types." (PMID 34782604, 2021).
ATP5F1D also shares sentences with these, for which no sentence is quoted: energy metabolism disorder (4 papers); Parkinson disease (4); Alzheimer disease (3); Huntington disease (2); infection (2); ischemia (2); Metabolic Disorder (2); varicocele (2); acute myeloid leukemia (1); amyotrophic lateral sclerosis (1); asthma (1); cardiac hypertrophy (1); Hypercholesterolemia (1); infertile (1); male infertility (1); myocardial infarction (1); preeclampsia (1).